RPL36AP26 (ribosomal protein L36a pseudogene 26)
Synonyms: RPL36A_8_787
Gene: Processed pseudogene on chromosome 7 (15,701,435 to 15,701,752, reverse strand). Ensembl gene ENSG00000235828.
Diseases named in the same sentence as RPL36AP26 in open-access papers:
RPL36AP26 is named in the same sentence as 1 disease in open-access papers, as found by Europe PMC text mining. Sharing a sentence is not in itself a finding about the gene and the disease.
RPL36AP26 shares sentences with these, for which no sentence is quoted: melanoma (1 paper).